IL6 (interleukin 6)
Diseases named in the same sentence as IL6 in open-access papers (continued):
Sharing a sentence is not in itself a finding about the gene and the disease.
cognitive decline (continued). "Circulating inflammatory factors, such as IL-6, are significantly increased before clinical onset of dementia and predict cognitive decline." (PMID 34094639, 2021). "Anesthesia/surgery can induce the innate immune system response and microglia activation, leading to the synthesis and release of inflammatory cytokines (e.g., TNF-α, IL-1β, and IL-6) and cognitive decline." (PMID 33541361, 2021). "Previous studies have shown that TNF-α and IL-6 levels increased postoperatively and were closely related to cognitive decline." (PMID 33836651, 2021). "In patients with cirrhosis and HE, proinflammatory cytokines, such as tumor necrosis factor α (TNF-α), interleukin 1β (IL-1β), and interleukin 6 (IL-6), modulate and have synergistic effects with ammonia during cognitive decline." (PMID 34937168, 2021). "It is possible that the reduction in AlloP with age is dependent on the elevation of IL-6 and is a major factor contributing to cognitive decline." (PMID 32669383, 2020). "A correlation has been shown between aging-related cognitive decline in healthy older adults and elevated plasma levels of IL-6 and Bax/Bcl ratio." (PMID 32059688, 2020). "In the Rotterdam Study, elevated levels of pro-inflammatory cytokines including IL-6 and CRP were found to be associated with cognitive decline and executive function." (PMID 32455946, 2020). "In previous publications we found that cognitive decline, inflammatory markers such as IL-6 and Iba-1, rotarod performance, and fibrosis was improved in this cohort of mice, suggesting that this dosage is sufficient to improve specific aging phenotypes." (PMID 32575074, 2020). "HMGB1 suppression with CRISPR/Cas9 knockout plasmid restored TNF-α, IL-1β, and IL-6 and attenuated hippocampal atrophy and cognitive decline." (PMID 32245271, 2020). "TNF-α and IL-6 influence the onset of frailty and cognitive decline, and CRP levels link muscle quality with cognitive function." (PMID 32257550, 2020). "Since neuroinflammation was closely related to cognitive decline after surgery, the levels of the proinflammatory cytokines IL-6 and IL-1β in the hippocampus were examined 24 h after tibial fracture surgery by ELISA." (PMID 31011286, 2019). "Overall, neuronal dysfunction and subsequently cognitive decline is perpetuated by inflammatory cytokines, such as IL-1β, IL-6 and TNF-α." (PMID 30374291, 2018). "In conclusion, these results add further evidence for the association between high peripheral inflammation, as measured by blood IL-6, with future cognitive decline." (PMID 29358917, 2017). "Specifically, those with high IL-6 were 1.42 times more likely to experience global cognitive decline, compared to those with low IL-6." (PMID 29358917, 2017). "Those with high baseline IL-6 were 1.42 times more likely to encounter global cognitive decline at follow-up, compared to those with low IL-6 (OR 1.42, 95% CI 1.18–1.70, p < 0.001)." (PMID 29358917, 2017). "Those with high circulating IL-6 were 1.42 times more likely to experience global cognitive decline at follow-up, over a 2–7-year period, compared to those with low IL-6 (OR 1.42, 95% CI 1.18–1.70; p < 0.001)." (PMID 29358917, 2017). "Serum or plasma biomarkers of inflammation, especially IL-6 and C-reactive protein (CRP), were prospectively associated with cognitive decline in multiethnic cohorts of older populations before the clinical onset of dementia, AD, and vascular dementia." (PMID 26682220, 2015). "In the ET2DS, higher levels of fibrinogen, TNF-α, and IL-6 but not CRP were associated with lower measures of cognitive function; higher baseline levels of fibrinogen and IL-6 additionally predicted a steeper 4-year cognitive decline." (PMID 26060511, 2015). "Although studies investigating the impact of IL-6 on cognitive decline in AD and patients are few, a couple of studies support the idea." (PMID 26434635, 2015).
cognitive decline (continued). "Using the Modified Mini-Mental State Examination (3MS) as a measure of cognitive function, the researchers evaluated serum levels of IL-6, CRP, and TNF-α at baseline in relation to baseline cognition and risk of cognitive decline over two years." (PMID 25793613, 2015). "Higher peripheral plasma IL-6 levels were associated with lower hippocampal grey matter volume in middle-aged subjects, suggesting a mediating role for peripheral IL-6 in cognitive decline." (PMID 26580647, 2015). "The altered brain expression of IL-6 in AD and DLB patients and the found link between elevated peripheral IL-6 and cognitive decline has led to studies attempting to monitor ongoing pathological neuroinflammation by analysing IL-6 concentration in CSF." (PMID 26434635, 2015). "Independently of POD onset, high-plasma level of IL-6 was also associated with poor functional status or ADL <6 (p = 0.030), with cognitive decline or SPMSQ ≤7 (p = 0.014), emergency admission (p = 0.023), and higher comorbidity or CIRS ≥8 (p = 0.046)." (PMID 25368603, 2014). "Extensive research has found that pro-inflammatory cytokines including IL-1β, IL-6 and TNF-α are strongly associated with cognitive decline and motor retardation particularly amongst elderly populations." (PMID 21799922, 2011). "Opioids may induce cognitive decline through neuroinflammation, increasing hippocampal inflammatory markers (IL-1β, IL-6, TNFα) observed in animal studies." (PMID 40657909, 2025). "This focus ensures that downstream sections, on pain biology, HPA feedback, BBB integrity, and therapeutic levers, cohere around a single, testable model, that being inflammation → IL-6/CRP → mCRP effector signaling → vascular–neuroimmune dysregulation → cognitive decline." (PMID 41373439, 2025). "In the context of glial cell activation, the GFAP-IL6 mouse model, which overexpresses IL-6 in astrocytes, demonstrates chronic neuroinflammation accompanied by significant neurodegeneration and cognitive decline, highlighting the pivotal role of astrocyte-derived IL-6 in AD." (PMID 40565005, 2025). "Notably, the disparities in their temporal progression and correlation with plasma IL‐6 indicate that sickness behavior and cognitive decline are distinct features of POCD." (PMID 39789906, 2025). "In population-based studies, increased circulating IL-6 levels have been shown to be co-occur with cognitive decline, and patients with psychostimulant-use disorders who show high circulating levels of IL-6 perform significantly poorer on tests of executive function tests." (PMID 38790414, 2024). "Similarly, IL-6 has been reported to be associated with aging as a marker of chronic inflammatory conditions, such as cognitive decline and physical performance decline, and IL-6 has also been reported to contribute to improved hepatic glucose tolerance." (PMID 38999780, 2024). "Furthermore, blood levels of C-reactive protein and IL-6 have also been shown to predict future cognitive decline." (PMID 39154864, 2024). "In addition, exercise has anti-inflammatory effects by reducing systemic inflammation, which is associated with cognitive decline, and lowering levels of C-reactive protein (CRP) and interleukin-6 (IL-6)." (PMID 39651037, 2024). "Several studies have also demonstrated an association between elevated levels of proinflammatory markers, including C-reactive protein, IL-6, and tumor necrosis factor-alpha (TNF-α), and cognitive decline as well as an increased risk of neurodegenerative disorders (e.g., AD and vascular dementia)." (PMID 38089627, 2023). "Several meta-analyses of prospective studies have demonstrated that the peripheral inflammatory factor IL-6 is associated with cognitive decline in adults without dementia." (PMID 37254162, 2023). "Several meta-analyses of prospective studies demonstrated that the peripheral inflammation factor IL-6 is associated with cognitive decline in adults without dementia." (PMID 37254162, 2023).
cognitive decline (continued). "Notably, IL-1β or IL-6 appear upregulated in AD and other neurodegenerative disorders and are correlated with cognitive decline." (PMID 37187754, 2023). "For example, elevated serum CRP-levels were associated with cognitive decline in elderly women, and serum levels of CRP, Interleukin-6 and Interleukin-10 were negatively associated with a composite score of executive function and processing speed, but not with verbal episodic memory." (PMID 37467176, 2023). "Elevated IL-6 levels in plasma and cerebrospinal fluid correlated with cognitive decline." (PMID 36159208, 2022). "However, evidence from both cross-sectional and prospective studies highlight that higher IL-6 levels are related with poorer cognitive performance and faster cognitive decline." (PMID 35486344, 2022). "To test this hypothesis, we examined 915 individuals aged 45–74 years at baseline and evaluated whether higher levels of 3 circulating proinflammatory mediators, TNF-α, IL-6, and hs-CRP, could be associated with cognitive decline after 10 years." (PMID 36195448, 2022). "Perioperative neutralization of either HMGB1 tumor necrosis factor α (TNFα), IL-1β, or IL-6 can block the development of postoperative cognitive decline but may also interfere with healing." (PMID 36778590, 2022). "A recent meta-analysis showed a significant difference between the level of inflammatory markers (such as IL-6, IL-1b, sTNF-R1 and 2) during cognitive decline, describing in particular an increase in their level in MCI and AD patients (compared to controls), both in CSF and blood." (PMID 33986423, 2021). "In addition, IL-6 increase is frequently associated with chronic low-grade inflammation, and, recently, a longitudinal study proposed IL-6 as a predictor marker of cognitive decline in late midlife." (PMID 33562601, 2021). "Elevated IL-6 in midlife is associated with cognitive decline whereas increased CRP levels did not predict the concurrent cognitive decline." (PMID 32455946, 2020). "The presence of systemic infections and increased blood (plasma or serum) concentrations of cytokines including interleukin 1β (IL1β), interleukin 10 (IL10), interleukin 6 (IL6), and tumour necrosis factor α (TNFα) have been associated with sAD and predict cognitive decline." (PMID 30902060, 2019). "In conclusion, our studies have proven that scutellarin alleviates Alzheimer’s-like pathology and cognitive decline by reducing Aβ levels in the brain and plasma, decreasing Aβ plaque associated gliosis and levels of proinflammatory cytokines TNF-α and IL-6, and attenuating neuroinflammation." (PMID 29642616, 2018). "As well as clinical data obtained from patients undergoing gastrointestinal surgery showed that serum HMGB1 and IL-6 levels was elevated post-surgery, and the increased post-operative HMGB1 and IL-6 levels were associated with the cognitive decline the occurs 1-week post-surgery." (PMID 30271319, 2018). "Conversely, raised IL-6 levels in the circulation may merely be a reflection of the neuroinflammatory processes occurring during neurodegeneration and cognitive decline." (PMID 29358917, 2017). "We hypothesized that a dietary pattern related to increased IL-6 concentration in midlife predicts accelerated cognitive decline in a large sample of middle-aged population." (PMID 26874911, 2017). "The aim of this study was to collate the current data from the literature and perform a meta-analysis for longitudinal studies reporting the association between baseline peripheral IL-6 and future cognitive decline in adults without dementia." (PMID 29358917, 2017). "Our study participants are relatively healthy and young, and therefore it appears unlikely that preclinical disease might generate the links of the small degrees of cognitive decline we observed with IL-6 and dietary habit." (PMID 26874911, 2017).
cognitive decline (continued). "Interleukin-6 (IL-6) was found to be increased systemically in patients suffering from these psychological diseases and correlates with the finding that old individuals that express more IL-6 develop cognitive decline more frequently." (PMID 27065209, 2016). "Findings indicated that participants in the highest tertile of IL-6 or CRP serum concentrations performed significantly worse at baseline and follow-up 3MS, with a 24% increase in risk of cognitive decline over the two year period in comparison to those participants in the lowest tertile." (PMID 25793613, 2015). "Our findings support previous studies by demonstrating a link between inflammatory processes and dementia progression and further strengthen the hypothesis that IL-6 is involved in dementia pathology and cognitive decline." (PMID 26434635, 2015). "Prolonged MV after surgery further aggravates cognitive decline that may stem from upregulation of hippocampal IL-1β, IL-6 and TNFα, partially via activation of gliocytes in the surgical mouse hippocampus." (PMID 25887955, 2015). "Our data suggest that prolonged MV further aggravates cognitive decline after surgery that may stem from upregulation of hippocampal IL-1β, IL-6 and TNFα, partially via activation of gliocytes in surgical mice." (PMID 25887955, 2015). "IL-6 and other cytokines may play an important role in the chronic inflammation and neurodegeneration characteristic of the cognitive decline." (PMID 25033379, 2014). "Besides, converging animal and clinical findings support a main role for IL-6 in mood disorders and cognitive decline." (PMID 21949705, 2011). "Similarly, this study showed a notable decline in IL-6, IL-1β, and TNF-α levels upon OPB administration at both high and low doses, indicating the potential of OPB to mitigate neuroinflammation associated with learning ability and cognitive decline." (PMID 41557677, 2026). "Moreover, P. gingivalis periodontal infection could cause cognitive decline by releasing proinflammatory cytokines, including tumor necrosis factor-alpha (TNF-α), interleukin (IL)-6, and IL-1β, in the brain." (PMID 40612448, 2025). "Additionally, ACEs may contribute to cognitive decline indirectly through depressive symptoms and chronic inflammation, reflected by elevated levels of interleukin-6 and C-reactive protein in adulthood." (PMID 40674657, 2025). "Thus, the multi-dimensional effect of NAT on markers like NFκB, CREB, Tau, SP, AChE, TNF-α, and IL-6 could suggest its ability to ameliorate the neuroinflammation-induced cognitive decline in AD." (PMID 38091207, 2024). "High IL-6 levels may affect the permeability of the blood–brain barrier, allowing more immune cells and inflammatory factors to enter the brain, exacerbating neuroinflammation and leading to cognitive decline." (PMID 39767857, 2024). "This study showed that IL-6 may be involved in early cognitive decline in elderly." (PMID 36805537, 2023). "In current study, elevated levels of IL-6, IL-1β, and TNF-α were positively associated with poorer cognition, especially in aged LPS and LPS-EE mice, demonstrating that increased systemic inflammation is closely related to cognitive decline during the accelerated aging." (PMID 36479357, 2022). "Moreover, HMGB1 suppression could decrease proinflammatory cytokines (TNF-α, IL-1β, and IL-6), attenuate hippocampal atrophy, and improve cognitive decline." (PMID 32245271, 2020). "Importantly, we previously found IL-6 to be upregulated both in the periphery as well as in the CNS, and administration of a selective monoclonal antibody was shown to prevent postoperative neuroinflammation and cognitive decline in this model." (PMID 31911786, 2019). "However, from a collective analysis containing 15,828 older adults who were community-dwelling at baseline, those with high baseline IL-6 were 1.42 times more likely to develop global cognitive decline during a follow-up period of 2–7 years, compared to those with low IL-6." (PMID 29358917, 2017).
cognitive decline (continued). "This study investigates the etiology of this association by performing meta-analyses on prospective studies investigating the relationship between baseline interleukin-6 (IL-6), an established marker of peripheral inflammation, with cognitive decline risk in non-demented adults at follow-up." (PMID 29358917, 2017). "The current findings that non-demented older adults with high baseline IL-6 are at an increased risk of future cognitive decline could make it possible of identifying at risk individuals." (PMID 29358917, 2017). "Finally, we investigated whether log-transformed IL-6 correlates with cognitive decline in patients with AD and patients with DLB." (PMID 26434635, 2015). "Thus, to better analyze the role and association of pro-anti-inflammatory cytokines with other parameters, independently of POD, we found significant higher levels of IL-6 in patients with compromised functional status, higher comorbidity, cognitive decline, and emergency admission." (PMID 25368603, 2014). "Emerging evidence highlights maladaptive microglial activation, chronic cytokine signaling (including IL-1β, TNF-α, and IL-6), and hypothalamic-pituitary-adrenal (HPA) axis hyperactivity as pivotal contributors to neuronal damage and cognitive decline." (PMID 41907842, 2026). "Analysis of all dialysis-induced cognitive decline cases revealed that the area under the ROC curve for α-klotho, FGF-23, IL-6, TNF-α, BDNF, BMI, and calcium were 0.58, 0.55, 0.58, 0.59, 0.70, 0.64, and 0.62, respectively." (PMID 40950978, 2025). "Inflammatory cytokines (e.g., IL-6, TNF-α) can negatively affect neuronal function, leading to cognitive decline." (PMID 40868579, 2025). "The best cutoff values for serum α-klotho, FGF-23, IL-6, TNF-α, BDNF, BMI, and calcium levels for the diagnosis of dialysis-induced cognitive decline were 469.5 pg/mL, 1,264.5 ng/mL, 1.8 pg/mL, 21.1 pg/mL, 20.0 ng/mL, 23.9 kg/m2, and 2.52 mmol/L, respectively." (PMID 40950978, 2025). "Among these markers are Interleukin-1α (IL-1α), Interleukin-1β (IL-1β), Interleukin-6 (IL-6), tumor necrosis factor-α (TNFα), and CCL2, contributing to microglial activation, synaptic irregularities, cognitive decline, and hindered adult neurogenesis." (PMID 40703771, 2025). "Subjects in the highest tertiles for IL-6 and CRP performed significantly worse on cognitive tests at follow-up than those in the lowest and had higher odds of cognitive decline over two years." (PMID 40805992, 2025). "Larger studies further associate chemotherapy-related increases in IL-6, TNF-α, and soluble TNF receptors with impaired physical function and fatigue, while smaller cohorts link IL-6 and MCP-1 elevations with cognitive decline." (PMID 41153842, 2025). "This process enhances the production of inflammatory mediators such as IL-1β, IL-6, IFN-γ, TNF-α, CCL2, GMF, NO, and ROS, ultimately driving inflammatory responses and cognitive decline in neurodegenerative diseases." (PMID 40556958, 2025). "The relationship between IL-6, BACE1, and cognitive decline underscores the central role of neuroinflammation in disease progression." (PMID 40748886, 2025). "They found that patients with persistently elevated IL-6 and TNF-alpha levels were more likely to experience significant cognitive decline in addition to physical disability." (PMID 39859987, 2025). "In line with these previous studies, the results showed that the levels of IL‐1β, IL‐6, and TNF‐α were increased in the hippocampus of the mice exposed to CSD, which contributed to the observed cognitive decline." (PMID 38688894, 2024). "With age, microglial cells the resident innate immune cells of the central nervous system—become chronically active, leading to sustained release of pro-inflammatory cytokines such as IL-6 and TNF-a, known as contributors to cognitive decline." (PMID 39446794, 2024).